FLVCR2 (FLVCR choline and putative heme transporter 2)
Description:
Choline uniporter that specifically mediates choline uptake at the blood-brain-barrier. Responsible for the majority of choline uptake across the blood-brain-barrier from the circulation into the brain (By similarity). Choline, a nutrient critical for brain development, is a precursor of phosphatidylcholine, as well as betaine (By similarity). Also mediates transport of ethanolamine. Choline and ethanolamine transport is not coupled with proton transport and is exclusively driven by the choline gradient across the plasma membrane. However, the presence of an inwardly directed proton gradient enhances choline uptake (By similarity). Also acts as a heme b transporter. Required to regulate mitochondrial respiration processes, ATP synthesis and thermogenesis. At low heme levels, interacts with components of electron transfer chain (ETC) complexes and ATP2A2, leading to ubiquitin-mediated degradation of ATP2A2 and inhibition of thermogenesis. Upon heme binding, dissociates from ETC complexes to allow switching from mitochondrial ATP synthesis to thermogenesis.
Synonyms: CCT; C14orf58; FLJ20371; MFSD7C; SLC49A2; EPV; FLVCRL14q; PVHH
Tractability: Small molecule: a structure with a bound ligand is known. Antibody: UniProt places it where antibodies can reach, with high confidence; its Gene Ontology location is reachable by antibodies, with high confidence; UniProt predicts a signal peptide or a membrane-spanning region. PROTAC: ubiquitination databases record sites on it; its protein half-life has been measured.
Gene: Protein-coding gene on chromosome 14 (75,578,594 to 75,663,214, forward strand). Ensembl gene ENSG00000119686.
Subcellular location: Cell membrane; Mitochondrion membrane; Endoplasmic reticulum membrane
Gene Ontology:
Molecular function: choline transmembrane transporter activity; ethanolamine transmembrane transporter activity; heme binding; heme transmembrane transporter activity; choline binding; transmembrane transporter activity
Biological process: choline transport; heme export; transport across blood-brain barrier; ethanolamine transport; transmembrane transport
Cellular component: endoplasmic reticulum membrane; mitochondrial membrane; plasma membrane; membrane
Genetic constraint (gnomAD): Loss-of-function variants: 26 observed, 40.08 expected, observed/expected ratio (o/e) 0.65, 90% interval 0.47 to 0.9. The upper end of that interval is the gene's LOEUF score, 0.9, which puts it in group 3 of 6, group 1 being the genes least tolerant of losing a copy. Missense variants: 623 observed, 666.16 expected, observed/expected ratio (o/e) 0.94, 90% interval 0.88 to 1. Synonymous variants: 244 observed, 262.76 expected, observed/expected ratio (o/e) 0.93, 90% interval 0.84 to 1.03.
Gene-disease validity (ClinGen):
ClinGen rates the evidence that FLVCR2 causes each of these diseases.
Fowler syndrome (autosomal recessive): Definitive.
Homologues: Orthologues: chimpanzee FLVCR2 (99% identical), macaque FLVCR2 (96% identical), dog FLVCR2 (90% identical), rabbit FLVCR2 (89% identical), pig FLVCR2 (87% identical), mouse Flvcr2 (87% identical), rat Flvcr2 (83% identical), guinea pig FLVCR2 (83% identical), zebrafish flvcr2b (57% identical), zebrafish flvcr2a (56% identical), tropical clawed frog flvcr2 (56% identical), Drosophila melanogaster HisT (42% identical), and 1 more. Paralogues in human: FLVCR1 (53% identical), SLC49A4 (23% identical), SLC49A3 (20% identical), CFAP276 (7% identical).
Diseases named in the same sentence as FLVCR2 in open-access papers:
FLVCR2 is named in the same sentence as 25 diseases in open-access papers, as found by Europe PMC text mining. Sharing a sentence is not in itself a finding about the gene and the disease. The quoted sentences say what the papers report.
Fowler syndrome (11 papers, 2014 to 2024). "Yet, loss of function of its paralog, FLVCR2, causes lethal hydranencephaly-hydrocephaly syndrome (Fowler Syndrome) which should be considered in the differential diagnosis for dystroglycanopathy." (PMID 38296890, 2024). "Mutations in FLVCR2 are associated with Fowler’s syndrome, a disorder characterized by HC and hydranencephaly." (PMID 38439105, 2024). "FLVCR1 mutations have been documented in patients with a rare neurodegenerative disorder, posterior column ataxia with retinitis pigmentosa, whereas FLVCR2 mutations are associated with Fowler syndrome, a rare proliferative vascular disorder of the brain." (PMID 36288320, 2022). "In humans, FLVCR2 mutations are related to Fowler syndrome, the cerebral proliferating vascular disease." (PMID 36313565, 2022). "Among all these heme importers, FLVCR2 is the only gene directly associated to a neurodegenerative disorder, the Fowler Syndrome." (PMID 30356807, 2018). "The present report confirms the genetic homogeneity of Fowler syndrome and describes a new FLVCR2 mutation affecting the protein function." (PMID 29500860, 2018). "Mutations in the FLVCR2 gene have been associated to the Fowler syndrome (OMIM: #225790), a rare lethal autosomal-recessive disorder of brain angiogenesis, first described in 1972." (PMID 24782769, 2014). "However, loss of function variants of its paralog FLVCR2 cause a syndrome characterized by proliferative vasculopathy and hydranencephaly-hydrocephaly, also termed Fowler Syndrome." (PMID 38296890, 2024). "Mutations in the orphan transporter MFSD7c (also known as Flvcr2), are linked to Fowler syndrome." (PMID 38302740, 2024). "Homology modeling of FLVCR2 structure suggests that the missense mutations related with Fowler syndrome affect transmembrane domains that may modify the channel proper function or folding." (PMID 30356807, 2018). "The Fowler syndrome is an autosomal recessive disorder caused by mutations in the FLVCR2 gene." (PMID 30356807, 2018). "SLC49A2 (FLVCR2), which is highly homologous to SLC49A1, but less so to SLC49A4, may be a plasma membrane heme importer, and it is mutated in patients with Fowler syndrome, a rare proliferative vascular disorder of the brain." (PMID 36456177, 2023). "A second hypothesis to explain FLVCR2 implication in the Fowler syndrome is based on its heme import activity." (PMID 24782769, 2014). "Finally, genetic studies in humans associated Flvcr2 mutation to the Fowler syndrome, a disorder with no obvious link to heme metabolism (see section Fowler Syndrome)." (PMID 24782769, 2014). "Several kinds of mutations were identified in cases of Fowler syndrome, but it is not clear how these mutations could affect FLVCR2 expression, functions or localization." (PMID 24782769, 2014).
acute myeloid leukemia (2 papers, 2022 to 2024). Acute myeloid leukemia (AML) is a group of neoplasms arising from precursor cells committed to the myeloid cell-line differentiation. "For instance, FLVCR2 has been proposed as a prognostic biomarker for acute myeloid leukemia due to its implication in the modulation of the tumor microenvironment in acute myeloid leukemia patients, specifically in terms of immune infiltration degree and cancer cell proliferation rate." (PMID 38432636, 2024).
Hydrocephalus (2 papers, 2018 to 2023). Hydrocephalus is an active distension of the ventricular system of the brain resulting from inadequate passage of CSF from its point of production within the cerebral ventricles to its point of absorption into the systemic circulation. "Moreover, defects in angiogenesis components such as FLVCR heme transporter 2 (FLVCR2) and Vascular endothelial growth factor (VEGF) in humans have been linked to hydrocephalus." (PMID 36859317, 2023).
lung carcinoma (2 papers, 2009 to 2024). "Similarly, the ratio between the heme/porphyrin exporter FLVCR1 and importer FLVCR2 genes indicates enhanced exporting function in lung cancers." (PMID 39062740, 2024).
low grade glioma (1 paper, 2022). A grade I or grade II glioma arising from the central nervous system. "FLVCR2 expression increased in tumors, such as renal papillary cell carcinoma, renal clear cell carcinoma, and low-grade glioma (LGG), compared to that in matched healthy samples, and FLVCR2 downregulation predicted the dismal OS for 518 LGG cases." (PMID 36313565, 2022).
ovarian carcinoma (1 paper, 2023). A malignant neoplasm originating from the surface ovarian epithelium. "Similarly, for iron export, lower expression levels of ABCG2, FLVCR1, and FLVCR2 were associated with an advanced stage of ovarian cancer." (PMID 38186569, 2023). "The expression of most genes involved in iron export, including ABCG2, FLVCR1, FLVCR2, and SLC40A1, was associated with improved PFS in ovarian cancer." (PMID 38186569, 2023). "Similarly, most genes involved in iron export, such as SLC40A1, FLVCR1, ABCG2, and MON1A, displayed reduced expression in ovarian cancer tissues; in contrast, only one gene, FLVCR2, showed the opposite trend." (PMID 38186569, 2023). "The expression of FLVCR2 and SLC40A1 involved in iron export was associated with improved OS in ovarian cancer, while the expression of MON1A in this process was associated with poor OS in ovarian cancer." (PMID 38186569, 2023).
prostate carcinoma (1 paper, 2022). A carcinoma that arises from epithelial cells of the prostate gland. "Additionally, FLVCR2 has been demonstrated as a potential biomarker for predicting prostate cancer progression, especially at stage II." (PMID 36313565, 2022). "Subsequently, FLVCR2 was found to be a potential biomarker for predicting prostate cancer." (PMID 36313565, 2022).
skin cutaneous melanoma (1 paper, 2022). "However, the expression level of FLVCR2 in skin cutaneous melanoma (SKCM) decreased relative to that in healthy samples, and low FLVCR2 expression predicted poor SKCM patient survival." (PMID 36313565, 2022).
cancer (5 papers, 2019 to 2024). A tumor composed of atypical neoplastic, often pleomorphic cells that invade other tissues. "For exploring FLVCR2 expression between cancer and healthy samples from several cancers, this study used web server TCGA and GTEx." (PMID 36313565, 2022). "The role of FLVCR2 in normal cells is not well-studied and to our knowledge there is only one paper to date in which FLVCR2 was analyzed in cancer." (PMID 32010627, 2019). "Furthermore, the gene essentiality analysis emphasized the significance of heme trafficking, exemplified by the heme importer FLVCR2, in cancer cells for at least in vitro survival." (PMID 39062740, 2024). "The gene essentiality analysis also highlighted the importance of heme trafficking (e.g., heme importer FLVCR2) and key hemoproteins (e.g., CYC1) in cancer cell survival." (PMID 38649187, 2024).
tumor (5 papers, 2021 to 2023). "According to our review of the literature, this study is the first to support the link between FLVCR2 and tumor immunity in AML." (PMID 36313565, 2022). "Our findings indicate that FLVCR2 may be an independent prognostic factor that influences tumorigenesis and tumor immunology in AML progression." (PMID 36313565, 2022). "This study provides insights into FLVCR2’s effect on tumor immunity, indicating that it might serve as an independent prognostic biomarker and was related to immune infiltration within AML." (PMID 36313565, 2022). "Therefore, upregulated FLVCR2 probably suppresses tumor immunity, which contributes to the escape of tumor cells and promotes carcinogenesis, indicating a possible mechanism by which FLVCR2 affects the OS of patients with AML." (PMID 36313565, 2022). "Some genes, like KHNYN, HBQ1, SCD5 and FLVCR2, may play roles in tumorigenesis, metabolism or tumor therapy." (PMID 34568059, 2021).
FLVCR2 also shares sentences with these, for which no sentence is quoted: breast carcinoma (2 papers); colon carcinoma (1); colorectal cancer (1); dystroglycanopathy (1); glaucoma (1); glioblastoma (1); hydranencephaly (1); infection (1); microcephaly (1); renal clear cell carcinoma (1); renal dysplasia (1); renal papillary cell carcinoma (1); retinitis pigmentosa (1); Sepsis (1); uveal melanoma (1).